IFNG (interferon gamma)
Diseases named in the same sentence as IFNG in open-access papers (continued):
Sharing a sentence is not in itself a finding about the gene and the disease.
Sepsis (continued). "Hence, the mechanism of action of IFNγ was elucidated, providing a new target for the immunotherapy of sepsis." (PMID 37434129, 2023). "It is speculated that IFNγ also reverses sepsis-induced immunosuppression through the PI3K/AKT/mTOR/HIF-1α pathway." (PMID 37434129, 2023). "In addition, inflammatory cytokines such as interleukin-1β (IL-1β), IL-6, IL-18, tumor necrosis factor alpha (TNF-α), and interferon-gamma (IFN-γ) have been reported to play an essential role in the development of sepsis and septic shock." (PMID 37359526, 2023). "IFNγ is a known sepsis immunostimulatory drug that can improve metabolism." (PMID 37434129, 2023). "Prior studies demonstrate that neutralization of IFNγ or deficiency of IFNγ receptor confer protection against ALI and/or lethality induced by LPS, sepsis/systemic inflammatory response syndrome, hyperoxia/mechanical ventilation, and respiratory viral infection." (PMID 35159372, 2022). "Besides, Th1 and Th17 cells were measured in PBMCs from sepsis patients by flow cytometry; interleukin 17A (IL‐17A) and interferon gamma (IFN‐γ) were determined in serum from sepsis patients by ELISA." (PMID 35262976, 2022). "It proposed a classification model in which IFNγ elevations >83pg/ml or low/moderate IFNγ-elevations <83pg/ml in conjunction with low IL1β <8pg/mml were associated with CRS whereas low IFNγ and IL1β >8pg/mml were consistent with sepsis with 97% accuracy." (PMID 35402259, 2022). "Since NK cells in septic patients have been shown to produce low levels of IFNγ and to have a decreased cytotoxicity activity, low levels of CISH may influence susceptibility to sepsis through an NK cell dependent mechanism." (PMID 34072601, 2021). "TNFα, IL-6, IFNγ, IL-1β and IL-10 were measured in brain of mice 6 h after induction of sepsis." (PMID 33608025, 2021). "Interestingly, though, there was a strong positive correlation between sepsis scores and plasma concentrations of IL-6, IFNγ and TNFα." (PMID 34440538, 2021). "In an in vivo sepsis study, RvD1 decreased IL-6, TNFα, IL-1β and IFNγ levels significantly." (PMID 33815391, 2021). "In this study, we showed that SRG3 overexpression polarizes hepatic macrophages toward an anti-inflammatory M2 phenotype and reduces the pro-inflammatory function of NK cells (i.e., IFNγ production), dampening the cytokine storm induced by LPS/d-GalN-induced sepsis." (PMID 33809795, 2021). "Moreover, we investigated the therapeutic application of M(IFNγ+LPS+IC) that dampen the production of pro-inflammatory cytokines in a mouse sepsis model." (PMID 31998290, 2019). "Finally, in the translational approach, we investigated the cytokine profiles in the blood serum of mice after adoptive transfer of M(IFNγ+LPS+IC) in a mouse sepsis model." (PMID 31998290, 2019). "In murine CLP-sepsis, human adipose-derived mesenchymal stem cells were able to modulate sepsis by downregulation of Th1-cell responses, associated with lower levels of pro-inflammatory cytokines (TNF, IL-1β, IL-6, IL-12, IFNγ) and higher levels of anti-inflammatory IL-10 derived from macrophages." (PMID 31114571, 2019). "We describe the effects of IFNγ in a cohort of 18 adult and 2 pediatric sepsis patients." (PMID 31690258, 2019). "Moreover, interferon gamma (IFNγ) administered in vivo or ex vivo to mouse or human monocytes obtained during sepsis reversed the phenotype of glycolysis deactivation and innate immune tolerance of monocytes." (PMID 30069485, 2018). "Notably, our results also suggest that therapies that restore APC functions (such as IFNγ as tested here) probably have a positive effect not only on innate immunity but also on adaptive immune cells after sepsis." (PMID 26642057, 2015). "Because interferon-gamma (IFN-γ) plays an important role in inflammation, this work assessed IFN-γ single nucleotide polymorphism (SNPs) that may be associated with sepsis." (PMID 24475220, 2014).
Sepsis (continued). "IFNγ induces HLA-DR expression by antigen-presenting cells, and this may be an important mechanism by which it reduces mortality in sepsis." (PMID 23935244, 2013). "Immunostimulation by granulocyte-macrophage colony-stimulating factor (GM-CSF) and interferon-gamma (IFN-γ) during the state of sepsis-induced immunosuppression might be a promising therapeutic option to reverse this anergy." (PMID 24093602, 2013). "To “pre-empt” the development of sepsis, these patients could receive prophylactic treatments, such as antibiotics, immunostimulant therapies using interferon-gamma or granulocyte-macrophage colony-stimulating factor, as proposed in septic shock." (PMID 22431998, 2012). "Notably, current understanding of sepsis can involve either IFNγ suppression or hyperactivity." (PMID 40762872, 2025). "In addition, the Warburg effect inhibitor 2-DG and PI3K inhibitor LY294002 were used to verify whether IFNγ in improving sepsis-induced immunosuppression through this pathway." (PMID 37434129, 2023). "Therefore, IFNγ has an inhibitory effect on LPS-induced sepsis-related cell apoptosis." (PMID 37434129, 2023). "Moreover, we also used glycolysis inhibitors (2-deoxy-d-glucose, 2-DG) and a PI3K inhibitor (LY294002) to investigate whether IFNγ reverses sepsis-induced immunosuppression by promoting the Warburg effect." (PMID 37434129, 2023). "IFNγ could also promote Bcl-2 and inhibit Bax expression in sepsis." (PMID 37434129, 2023). "Immune suppression in sepsis and a decrease in inducible lymphocyte IFNγ gene production may alternatively be related to T-cell apoptosis, expression of inhibitory signalling molecules, and the exaggerated effects of regulatory T cells or a decrease in T-cell repertoire." (PMID 23935244, 2013). "Age inversely correlated with the percentage of CD8+ T cells positive for IFNγ in sepsis alone (r2 = 0.16, p=0.04) and the percentage of CD8+ T cells positive for TNFα in sepsis alone (r2 = 0.22, p=0.013)." (PMID 39935482, 2025). "Correlation analyses of MAIT cell activation markers and soluble factors in sepsis patients revealed positive, albeit weak, correlations between the MAIT cell CD69 expression and the levels of IL‐12 and IL‐15 and with IFNγ and TNF in the plasma." (PMID 40041474, 2025). "The MAIT cell‐activating cytokines IL‐12, IL‐15 and IL‐18, as well as TNF, IFNγ and IL‐17A, cytokines known to be produced by MAIT cells, were elevated in the plasma of sepsis patients as well as non‐sepsis patients, compared with non‐infected controls." (PMID 40041474, 2025). "Plasma levels of IL‐12, IL‐15, TNF, IFNγ and CXCL10 correlated with the magnitude of MAIT cell activation in sepsis patients." (PMID 40041474, 2025). "In an experimental model of sepsis, nanoscale-sized graphene oxide (NGO)-mediated anti-inflammatory responses correlate with decreased IFNγ and IL4 secretion but increased TGFβ production by glycolipid-reactive invariant natural killer T (iNKT) cells." (PMID 39199350, 2024). "Supporting this, a study indicated that IFNγ enhances glycolysis via the PI3K/Akt/mTOR pathway, which potentially counters spleen immunosuppression during sepsis." (PMID 38259439, 2023). "Various agents, including granulocyte colony-stimulating factor (G-CSF), granulocyte-macrophage colony-stimulating factor (GM-CSF), and interferon-gamma (IFN-γ), have been investigated for their potential role in sepsis-induced DIC." (PMID 37834771, 2023). "Comparing the survival rate of CLP group with IFNg + CLP group, IFNg can improve the survival rate of mice with sepsis and 2-DG decreases the survival rate of mice." (PMID 37434129, 2023). "These macrophages are responsible for reducing cytokine levels, including IFNγ, TNF, IL-6, and IL-10, in patients with sepsis." (PMID 38193079, 2023). "Tolerant monocytes from sepsis patients show an impair levels of OXPHOS and glycolysis and IFNγ can restore the metabolic defects through activation of mTOR." (PMID 35154105, 2022).
Sepsis (continued). "It has been reported that serum cytokines such as IL-1β, IL-6, IL-8, IL-10, IL-12, IL-17A, IL-18, interferon gamma (IFN-γ), and TNF-α are elevated in sepsis, but some of these cytokines are also elevated in FMF patients." (PMID 34654467, 2021). "Just as seen with the 2W1S-specific memory CD4 T cells, CLP-induced sepsis led to a significant reduction in OVA323-specific memory CD4 T cell numbers and ability to produce IFNγ after in vivo restimulation." (PMID 32903436, 2020). "However, dose-dependent l-arginine supplementation in vitro increased CD4+ and CD8+ proliferation and enhanced secretion of T cell-related cytokines, such as IFNγ, suggesting that arginine supplementation at specific time points after sepsis may warrant further investigation." (PMID 31722736, 2019). "Serum cytokines, including IL6, IFNγ, IL1β, IL10, and TNFα were high suggesting the onset of sepsis in most of these mice even though there was a high degree of variation of bacterial load." (PMID 31121001, 2019). "Induction of sepsis by CLP resulted in early 1.5–20-fold increases in IL-6, IL-10, IFNγ and TNFα over that induced by sham surgery." (PMID 28724977, 2017). "Nor was there supernatant evidence that interphase neutrophils from sepsis patients produced cytokines (IL-2, IL-4, IL-6, IL-10, TNF or IFNγ) when cultured in vitro (unstimulated total cells or enriched CD66b + interphase neutrophils)." (PMID 25084831, 2014). "Severe sepsis differed from infection by having decreased IL7, IL23, IFNγ, and TNFα gene expression." (PMID 23935244, 2013). "This cytokine gene expression index consisted of the difference in log mRNA copy numbers for cytokines that were decreased in sepsis, namely, IFNγ, TNFα, IL7, and IL23, and the cytokine increased in sepsis, namely, IL10 (IFNγ + TNFα + IL7 + IL23–IL10)." (PMID 23935244, 2013). "In a multivariate nominal logistic regression model comparing gene expression in patients with infection and those with sepsis at ICU admission, IL10 (P = 0.02), IFNγ (P < 0.0001), and TNFα (P = 0.03) retained statistical significance." (PMID 23935244, 2013). "An algorithm utilising mRNA copy number for TNFα, IFNγ, IL7, IL10, and IL23 accurately distinguished sepsis from severe sepsis with a receiver operator characteristic value of 0.88." (PMID 23935244, 2013). "For example, interferon gamma (IFN-γ) administration reduces the frequency of serious infections in people with chronic granulomatous disease and can restore monocyte functionality in people with sepsis." (PMID 40447280, 2025). "Here, we tested the hypothesis that ex vivo functional TNF expression as well as an immunologic endotype based on both IFNγ and TNF expression could be used to model clinical outcomes in sepsis patients." (PMID 39469706, 2024). "In this study, we tested the hypothesis that whole blood ex vivo functional TNF expression alone as well as an immunologic endotype based on both IFNγ and TNF expression could be used to identify clinical outcomes in sepsis patients." (PMID 39469706, 2024). "Our results also demonstrated that IFNγ treats sepsis by promoting the Warburg effect through the PI3K/AKT/mTOR pathway by reducing the damage, immunosuppression, and metabolic paralysis brought about by sepsis." (PMID 37434129, 2023). "Pro-inflammatory cytokines, such as IFNγ, which are normally released in response to CLP-induced sepsis, may have been suppressed by TGF-β1, resulting in an impaired immune response and undesirable outcome." (PMID 36530874, 2022). "For instance, immune-stimulatory agents such as interleukin (IL) 7, granulocyte macrophage-colony stimulating factor (GM-CSF), and interferon gamma (IFN-γ) could restore lymphocyte and monocyte function and reverse sepsis-induced immunosuppression." (PMID 32691839, 2020).
Sepsis (continued). "During sepsis, the “cytokine storm” mediates the initial pro-inflammatory phase by releasing proinflammatory cytokines, such as IL-1α, IL-1β, tumor necrosis factor-α (TNF-α), IL-6, and interferon gamma (IFN-γ), among others." (PMID 32630422, 2020). "Of note, pre-treatment with Rhodiola rosea extract led to further increases in Th1 cytokines (IFNγ, IL-2 and IL-12; all P<0.05), while Th2 cytokine levels were not significantly altered compared with those in the model (sepsis) group." (PMID 26063084, 2015). "Animals from the various SIRS/sepsis groups featured fluctuations, albeit not significant, in numbers of Ag-specific IFNγ+ CD4+ T-cells, probably reflecting the individually distinct early loss of relevant naive T-cell precursors (data not shown)." (PMID 25541945, 2014). "In this study it was notable that decreased IFNγ gene expression characterised severe sepsis rather than infection." (PMID 23935244, 2013). "The rested cells from patients with sepsis, but not controls, had significantly greater secretion of IFNγ (rested: 16.1 ± 23.1 pg/ml versus no rest: 5.7 ± 15.7 pg/ml P < 0.01)." (PMID 22742734, 2012). "A key distinction may be the absence of profoundly elevated cytokine (mainly IL-6 and interferon-gamma) levels in sepsis, which are distinguishing features of the cytokine storm in CRS, particularly in the appropriate clinical context." (PMID 40277755, 2025). "In the present study, we find that CD69 expression correlates both with cytokines stimulating MAIT cell activation and with cytokines produced by MAIT cells, such as IFNγ and TNF, which may indicate that MAIT cells contribute to the pro‐inflammatory cytokine response in sepsis." (PMID 40041474, 2025). "Furthermore, the rate of IFNg production after anti-CD3/anti-CD28 stimulation did not significantly differ between sepsis and non-sepsis groups over the study period, although the mean cytokine concentrations did show notable differences between groups." (PMID 39712015, 2024). "Additionally, while TNFα, IL1β, and IFNγ are seen in human sepsis, they are considered to be pro-inflammatory cytokines, and not sepsis-specific." (PMID 37175585, 2023). "A recent report comparing patients with and without sepsis of unspecified origin indicates differential methylation at genes that participate in interferon-gamma-mediated (IFNγ) signaling, MHCII antigen processing and presentation, immunoglobulin production, and cell adhesion pathways." (PMID 34034806, 2021). "Furthermore, we investigated serum IFNγ/IL10 of propensity score matched patients from the placebo arm of the randomized placebo-controlled trial of Sodium Selenite and Procalcitonin-guided antimicrobial therapy in Severe Sepsis (SISPCT)." (PMID 33767693, 2021). "We asked whether our M(IFNγ + LPS, TNFα) signature could be used to predict the complication of dengue infection into a hemorrhagic outcome, the drug response in HIV positive patients, and sepsis resolution in children." (PMID 26302899, 2015). "The pathogenesis of sepsis is attributable, at least in part, to dysregulated systemic inflammatory responses characterized by the excessive accumulation of various proinflammatory mediators, such as tumor necrosis factor (TNF) or interleukin (IL)-1, interferon-gamma (IFN-γ), and nitric oxide (NO)." (PMID 24098466, 2013). "However, the production of IFNγ by CD4+ and CD8+ T cells in whole splenocyte preparations from septic mice 2 days after CLP was strongly reduced upon in vitro stimulation with anti‐CD3 antibodies, reflecting the previously observed impaired cytokine production in sepsis." (PMID 26734459, 2015).
Sepsis (continued). "First, biomarkers of T-cell activation and IFNγ-activity (e.g. GZMB, PDL1, LAG3, CXCL9) were present broadly in IHF, including hyperferritinemic sepsis, and were not unique to one diagnosis (PC1)." (PMID 39264477, 2024). "However, 2-DG inhibited the expression of Bcl-2 and Bax during sepsis; LY294002 did not affect Bax expression even after IFNγ treatment." (PMID 37434129, 2023). "Although LPS stimulation could activate both NK and NKT cells to secrete cytokine IFNγ through the TLR4 signaling pathway, SRG3 overexpression appeared to diminish the activation of NK cells but not NKT cells in LPS-induced sepsis." (PMID 33809795, 2021). "Our observation that hMSCs can suppress IL-2, IL-6 and TNF but not IFNγ is consistent with a previous finding in which administration of mMSCs reduced serum levels of IL-6 and TNF but not that of IFNγ in a cecal ligation and puncture model of sepsis." (PMID 24423010, 2014).